MUC1 (mucin 1, cell surface associated)
Diseases named in the same sentence as MUC1 in open-access papers (continued):
Sharing a sentence is not in itself a finding about the gene and the disease.
adenocarcinoma (continued). "Our data demonstrating the responsiveness of the MUC1/SEC isoform expression in human epithelial cells to inhibitory effects of 4-OHT are in agreement with observations that the expression of MUC1 gene in human adenocarcinoma cells is also sensitive to antiestrogens." (PMID 17083744, 2006). "Comparative profiling revealed higher EGFR and EPCAM expression in HNSCC versus NSCLC, while MUC1 predominated in NSCLC, particularly in SQCCL; notably, the NSCLC cohort was predominantly adenocarcinoma." (PMID 42203995, 2026). "MUC1/EMA is the major carrier of sLex in serous borderline ovarian cancer, adenocarcinoma, and micropapillary bladder urothelial carcinoma, whereas sLex is an epitope of MUC1/EMA15,16." (PMID 33893728, 2021). "One of these mucins, the polymorphic epithelial mucin (PEM) or MUC1, is found to be expressed in all human epithelial cells of adenocarcinomas as well as multiple hematological malignancies." (PMID 33670011, 2021). "Conversely, NKX2-1 and mucins (MUC1, MUC5B) were more highly expressed in adenocarcinoma, as were ROS1 and CLDN3." (PMID 32381040, 2020). "We have generated the PDA.MUC1 mice by breeding the Cre-LSL-KRASG12D to a human MUC1.Tg mice (designated KCM mice) that develop the entire spectrum of PanIN lesions and adenocarcinoma mimicking the human disease." (PMID 29462213, 2018). "In contrast, MUC1 is overexpressed and the VNTR is severely hypoglycosylated in all stages of development of adenocarcinoma and in various chronic inflammatory diseases including IBD." (PMID 29285251, 2017). "Aptamer MUC-1 selected by protein-SELEX targets mucin (MUC-1), which is highly expressed by the majority of human adenocarcinomas." (PMID 27973403, 2016). "A combination of “generic” adenocarcinoma markers (CK7, CK19, BerEP4, and polyclonal CEA) together with vimentin and a limited number of “pancreatobiliary” markers (MUC1 and CA19-9) defines its characteristic immunohistochemical profile." (PMID 27829047, 2016). "Carbohydrate antigen (CA) 15–3 (Mucin 1, MUC1), the product of the mucin 1 gene, is a large transmembrane glycosylated molecule aberrantly overexpressed in many adenocarcinomas in an underglycosylated form and then shed into the circulation." (PMID 22726603, 2012). "Combining MUC1 and/or MUC4 expression at these levels (MUC1 > 40% and/or MUC4 > 0%, versus MUC1 < 40% and MUC4 = 0%) indicated a clear survival disadvantage for patients with pancreatobiliary differentiated adenocarcinomas (P = 0.009)." (PMID 19236510, 2009). "Immunohistochemistry of the CT-guided liver biopsy was consistent with an adenocarcinoma of the pancreaticobiliary system: positive for mucin-1 (MUC1), but negative for MUC2, MUC5AC and prostate-specific antigen." (PMID 40419900, 2025). "Increased mucin expression, especially MUC1 and MUC4, occurs in many adenocarcinomas." (PMID 28177878, 2017). "A recent evaluation of differential expression of mucin-associated glycans during colon carcinogenesis showed that MUC1-Tn and MUC1-STn are overexpressed in premalignant polyps, advanced adenoma, and adenocarcinoma, but not on the normal colon." (PMID 27754373, 2016). "Since all metastatic PCs will progress to CRPC as either adenocarcinoma or NEPC, it will be interesting to examine whether metastases with genomic alterations only in the MUC1 network will progress into NEPCs." (PMID 27825118, 2016). "Of the 12 adenocarcinomas spots which were examined, 7 showed weak staining of MUC1 while in others expression was completely absent." (PMID 24671186, 2014). "In total, four out of the eight ampullary SRCs showed poorly differentiated adenocarcinoma with prominent signet ring cell features; of these, three showed CK7+, CK19+ and MUC1+ staining (cases 5, 3 and 6) and one case showed positive immunoreactivity for CD10 (case 3)." (PMID 25202392, 2014).
adenocarcinoma (continued). "Adenocarcinomas of the breast usually express MUC1 but not MUC2, whereas gastrointestinal adenocarcinomas frequently express MUC2 but less frequently express MUC1." (PMID 23938020, 2013). "The results of this analysis were confirmed by Cox regression analysis adjusting for possible confounders, demonstrating that MUC1 and/or MUC4 expression was indeed an independent prognostic factor among patients with pancreatobiliary differentiated adenocarcinomas." (PMID 19236510, 2009). "These cells were stimulated by a number of factors to produce mature DCs, and then pulsed with Wilms tumor gene 1 (WT1) peptide and Mucin 1 (MUC1), this vaccine was shown to be effective in a Phase I/IIa Clinical Trial in patients with adenocarcinoma without AEs of grade 2 or higher." (PMID 34631558, 2021). "Because the expression of hypoglycosylated MUC1 has been associated with highly inflamed colon tissues and all stages of adenocarcinoma, we also analyzed the expression of human hypoglycosylated MUC1 using the VU-4H5 antibody that specifically detects non-glycosylated PDTRP epitope." (PMID 29285251, 2017). "Our results showed that more than 90% of cases diagnosed as primary adenocarcinoma of the gallbladder were positive for CK7 (97.6%), CK19 (98.2%), CKLMW (100%), CKHMW (91.6%), or MUC1 (97.1%) expression, or were negative for vimentin (96.1%) or MUC2 (96.9%)." (PMID 33494186, 2021).
infection (112 papers, 2008 to 2026). The state of being infected such as from the introduction of a foreign agent such as serum, vaccine, antigenic substance or organism. "The flagellin from this bacter activates NEU1, which desialates MUC1 and other cell surface receptors, making it easier for P.Aeruginosa to bind and increase infection risk." (PMID 39469649, 2024). "Tumour necrosis factor alpha (TNF-α) is the key regulator of MUC1 expression in the pathogenic infection of airway epithelial cells." (PMID 38036963, 2023). "Deficiency in Muc1 also predisposed mice to infection with the gastrointestinal pathogen C. jejuni and the gastric pathogen H. pylori." (PMID 35774401, 2022). "Infection assays showed that StcE treatment of MUC1-ΔCT caused a 2.3-fold increase in the number of E. coli inv-infected DOX+ MUC1-ΔCT cells compared to 1.2-fold for the DOX− MUC1-ΔCT cells." (PMID 33824202, 2021). "The greater bacterial burden in the MUC1-deficient mice continued at 24–72 h of infection, and we observe this pathway to be potently activated at 24 and 72 h of infection in the gastric tissue of Muc1−/− mice compared with WT mice." (PMID 32793510, 2020). "We have shown that mice deficient in MUC1 are more susceptible to infection by H. pylori and that differences emerge very early in infection and are sustained, with characteristically more severe chronic inflammation." (PMID 32793510, 2020). "In in vivo infection experiments, Muc1 knockout mice showed increased susceptibility to H. pylori and C. jejuni with more severe epithelial damage, but did not display increased susceptibility to Salmonella Typhimurium infection." (PMID 30716138, 2019). "Muc1−/− mice are more susceptible to infection with Campylobacter jejuni, whereas bovine Muc1 inhibits binding of Escherichia coli, Staphylococcus aureus and Bacillus subtilis to Caco-2 cells." (PMID 31387973, 2019). "Muc1−/− mice were predisposed to developing bacterial conjunctivitis due to infections by Staphylococcus, Streptococcus, or Corynebacterium compared with Muc1+/+ mice." (PMID 29186029, 2017). "Some are down-regulated, such as cell surface associated (MUC1), which protects the body from infection by binding to pathogens." (PMID 21689475, 2011). "We have shown that mice deficient in Muc1 are more susceptible to infection by both H. pylori and Campylobacter jejuni." (PMID 19816567, 2009). "Previously we have shown that mice deficient in Muc1 are more susceptible to infection by H. pylori both with regard to the level of colonisation and the degree of pathology that develops." (PMID 19816567, 2009). "Meanwhile, gene expression analysis revealed that in the ΔsaaS group, Muc1 (encoding Mucin-1) had higher expression at 6 hpi; Muc2 (encoding Mucin-2) had higher expression throughout infection; while Muc4 (encoding Mucin-4) had higher expression at 72 hpi and 120 hpi." (PMID 37158502, 2023). "Previous work in CHO cells suggested that the ectodomain of ectopically expressed MUC1 could act as a releasable decoy that is shed upon IAV binding to prevent subsequent infection of underlying cells." (PMID 35699372, 2022). "The importance of the mucus barrier function is illustrated by the fact that mice lacking MUC2 develop spontaneous inflammation of the colon and similarly, deficiency in cell-surface mucin MUC1 makes mice more susceptible to severe infection with H. pylori or Campylobacter species." (PMID 33050171, 2020). "PA initiates infection through flagellum and type IV pili adherence, interacting with MUC1 ectodomains via NEU1 modulation." (PMID 41164165, 2025). "In gECs, E. gingivalis infection increased mucin (MUC1: 3.6×, MUC21: 14.4×) and interleukin secretion (IL-8, IL-1B: >6×, P = 0.019)." (PMID 40116481, 2025). "In the case of Adenovirus, which continues to amplify in HEK293T cells after infection, we showed that MUC1 on the cell surface has an inhibitory effect on long-term cumulative infection." (PMID 41147561, 2025).
infection (continued). "While the molecular mechanism of MUC1-ED desialylation mediated recruitment of NEU1 under Pa infection is still unclear." (PMID 38500102, 2024). "The infection of healthy human PBMCs with rAdF35-MUC1 resulted in a significant reduction in the number of false positives, suggesting that the MUC1 promoter offers high specificity for CTC detection." (PMID 39886667, 2024). "MUC1, the first mucin to be structurally elucidated, has been increasingly recognized for its role in protecting against infection as part of the body’s mucosal barrier." (PMID 38886669, 2024). "Muc1 has been observed to help prevent infection by playing a role in mucosal defense and acting as a decoy receptor." (PMID 39022518, 2024). "PCVV infection was lower in cells expressing high amounts of MUC1, compared with uncoated VV; however, aMUC1-PCVV resulted in restoration of infection." (PMID 38009779, 2023). "MUC1 − / − mice likely showed higher Pneumococcal loads and severe airway inflammation during infection with Streptococcus pneumoniae, as compared to WT mice." (PMID 38036963, 2023). "Compared with wild-type (WT) mice, MUC1 knockout mice showed increased airway inflammation during infection with P. aeruginosa." (PMID 38036963, 2023). "Mucin 1 (MUC1), a transmembrane epithelial glycoprotein, has been shown to function as a physical barrier in limiting pathogen infection and colonisation and exerts anti-pathogenic activities by suppressing inflammatory responses." (PMID 38036963, 2023). "The protective barrier provided by MUC1 was affected, leading to a reduced ability of the tissue to heal and resist infection." (PMID 36359337, 2022). "Given the ability of IAV to bind MUC1 during infection, and our observed changes in MUC1 protein dynamics in both HAE and PMD macrophages as a consequence of IAV infection, we next sought to determine the impact of MUC1 on IAV replication." (PMID 35699372, 2022). "Taken together, our results suggest that influenza virus interacts with MUC1 during the early stages of infection in a physiologically relevant system that recapitulates the extracellular environment in the airway." (PMID 35699372, 2022). "Since IAV can produce new virions as early as 6 h, this implies that there is a significant delay in both the timing and success rate of productive infection initiation in control cultures relative to MUC1-depleted cultures." (PMID 35699372, 2022). "The protective function of mucins against 229E and PIV3 infection was further confirmed for MUC1- and MUC4-overexpressing cells." (PMID 35879412, 2022). "MUC1 has been demonstrated to play a dynamic role in protection of the host from infection by a wide variety of pathogens and to regulate inflammatory responses to infection, while MUC2 has been shown to be important in the establishment of the mucus layer." (PMID 36676016, 2022). "At 3 days post-infection, MUC1 expression on ileal enterocytes was mainly detectable among infected mice and colocalized with 042 strains on the enterocyte surface." (PMID 35706909, 2022). "Claudin 1 (CLDN1) supports intercellular barrier function of tight junctions, and mucin 1 (MUC1) is located on the cell surface to provide a barrier to infection." (PMID 35202261, 2022). "MUC1 is rapidly stimulated at the surface of epithelial cells and macrophages on infection, and is thought to act as a “releasable decoy”, preventing virus from attaching and infecting the cells, thereby reducing viral infectivity." (PMID 34066999, 2021). "Here, we use the 4000 joint posterior distributions to predict the impact of MUC1 on some key infection-related quantities that likely influence infection severity." (PMID 34066999, 2021). "Firstly, MUC1, as part of the innate immune response, has been shown to be rapidly up-regulated within a few hours post in vitro infection." (PMID 34066999, 2021). "We compared the key estimation results of MUC1’s effects and model predictions of infection-related quantities between the two models." (PMID 34066999, 2021).
infection (continued). "We also use the data-calibrated models to evaluate and analyze the dependence of various infection-related quantities on MUC1 expression." (PMID 34066999, 2021). "Comparison of infection of DOX− MUC1 cells with the MUC1-positive subset of cells in the DOX+ MUC1 cell population yielded 40% infected cells for the MUC1-negative cells (Q3/Q3+Q4) and 50% infected cells for the MUC1-expressing cells (Q2/Q1+Q2)." (PMID 33824202, 2021). "The animals with high muc1 expression bound more H. pylori to their mucins but had lower rates of infection." (PMID 34488629, 2021). "Infection assays showed that StcE treatment increased bacterial invasion in the DOX+ MUC1-YF cells by 2.4-fold, compared to 1.6-fold for the DOX− MUC1-YF cells, resulting in comparable infection percentages in the two conditions." (PMID 33824202, 2021). "This suggested that inclusion of MUC1 peptide in the infection media to compete with cellular MUC1 did indeed impact the cell binding of aMUC1-PCVV to CAPAN-2 cells." (PMID 33869742, 2021). "With the MUC1 peptide incubated in the infection media, a 2-fold knockdown in infection was seen with MUC1-aMUC1-PCVV (2.4 × 105 [±1 × 105] a.u./g protein) when compared with aMUC1-PCVV (p = 0.003)." (PMID 33869742, 2021). "Incubation of DOX+ MUC1 cells with 75 μM genistein for 30 min prior to bacterial infection and for the entire 2 h infection period reduced the number of E. coli-infected MUC1-positive cells by 34%." (PMID 33824202, 2021). "Infection assays of confluent HT29-MTX cells with S. Enteritidis showed that the S. Enteritidis giant adhesin SiiE conferred interaction with MUC1, enabling efficient apical invasion into intestinal epithelial cells." (PMID 33824202, 2021). "MUC1 has been shown to interact with H. pylori during infection to block the bacteria from binding directly to the epithelial cells while activating the host inflammatory response." (PMID 31941061, 2020). "In the GCN analysis, Cluster007 showed reduced expression overall in Muc1−/− compared to wild type sham and also reduced further as the infection progressed." (PMID 32793510, 2020). "MUC1 extends 100 nm from the plasma membrane, localizes around microvilli, and has been shown to play an important defensive role during infection by various bacterial pathogens." (PMID 33184103, 2020). "The time course analysis of this study showed the induction of a potent anti-pathogen response within 24 h of H. pylori infection, with infection in Muc1−/− mice characterized by higher induction of INFG-regulated target genes." (PMID 32793510, 2020). "In contrast, Muc1−/− mice showed a greater number of down-regulated genes than WT after 24 h infection, and the number of down-regulated genes surpassed the number of up-regulated genes throughout the time course in Muc1−/− mice." (PMID 32793510, 2020). "This association was substantiated by the GCN analysis which revealed clusters of genes in which expression patterns were distinct in Muc1−/− mice at 24 and 72 h infection, and Muc1−/− sham and 8 h expression was similar to WT 24 and 72 h expression." (PMID 32793510, 2020). "Consistent with observation of MUC1-suppressed lipid metabolism in uninfected mice, 8 h infection further induced expression of a wide range of lipid transporters in the gastric tissue of Muc1−/− mice compared with WT." (PMID 32793510, 2020). "The higher CFU bacterial burden in the Muc1−/− mice persisted, being 2.5- and 2.8-fold higher at 24 and 72 h post-infection." (PMID 32793510, 2020). "Various papers have demonstrated that MUC1 plays an anti-inflammatory role during infection with P. aeruginosa." (PMID 33184103, 2020). "Uninfected Muc1−/− gastric tissue was highly enriched for expression of factors involved in lipid metabolism and 8 h infection further activated this network compared with WT." (PMID 32793510, 2020). "Differentially expressed 10 top genes in the Gastric Muc1−/− vs WT (KO/WT) or 72 h infection vs Sham (72h/0h) in WT or Muc1−/− (KO)." (PMID 32793510, 2020).